ACAT1 (acetyl-CoA acetyltransferase 1)
Diseases named in the same sentence as ACAT1 in open-access papers (continued):
Sharing a sentence is not in itself a finding about the gene and the disease.
gastric cancer (2 papers, 2024 to 2025). A primary or metastatic malignant neoplasm involving the stomach. "A receiver operating characteristic (ROC) curve was constructed to examine the diagnostic significance of ACAT1 expression by comparing ACAT1 expression in normal tissue specimens (data obtained from GTEx) and adjoining gastric cancer tissues with that of gastric cancer specimens." (PMID 39247186, 2024). "To explore the function of ACAT1 in gastric cancer, we analyzed three different gastric cancer cell lines: MKN45, N87, and AGS." (PMID 39247186, 2024). "The results showed that ACAT1 is expressed at significantly lower levels in gastric cancer tissues than in the adjacent benign tissues." (PMID 39247186, 2024). "To determine if overexpression of ACAT1 affects the invasive potential of gastric cancer cells, we used Transwell assays." (PMID 39247186, 2024). "The xenotransplantation results in nude mice showed that overexpression of ACAT1 in gastric cancer cells inhibited tumor growth in vivo." (PMID 39247186, 2024). "ACAT1 mRNA expression was notably reduced in primary tumor samples of gastric cancer compared to normal tissue samples." (PMID 39247186, 2024). "The expression of CD44 and OCT4 was decreased, while CD24 expression was increased by overexpressing ACAT1 in MKN45 gastric cancer cells." (PMID 39247186, 2024). "The TCGA database was used to make predictions about the patterns of ACAT1 mRNA expression in gastric cancer and normal tissue specimens." (PMID 39247186, 2024). "Immunofluorescence staining confirmed the presence of CD44 and CD24 proteins on the surface of gastric cancer cells, showing that increased ACAT1 levels suppress CD44 expression and enhance CD24 expression." (PMID 39247186, 2024). "The relationship between the ACAT1 gene expression and 24 distinct immune cell subtypes in gastric cancer was investigated and analyzed." (PMID 39247186, 2024). "Thereafter, we conducted soft agar anchorage-independence colony formation assay using MKN45-LV5 and MKN45-ACAT1 cells to investigate the influence of ACAT1 on the colony-forming potential of gastric cancer cells." (PMID 39247186, 2024). "We also analyzed the correlation of ACAT1 expression with clinical features of gastric cancer patients through the UALCAN database." (PMID 39247186, 2024). "Overexpression of ACAT1 in gastric cancer cells resulted in decreased expression levels of CD44 and OCT4, while the expression level of CD24 increased." (PMID 39247186, 2024). "In the current study, we found that the expression of ACAT1 in primary late-stage gastric cancer tumor tissues was significantly lower than in early-stage tumors." (PMID 39247186, 2024). "In further support of tumor-suppressor role in gastric cancer, we also found that ACAT1 negatively regulates EMT." (PMID 39247186, 2024). "ACAT1 expression was found to be decreased in gastric cancer tissue specimens compared to normal tissue specimens and adjoining gastric cancer tissues, based on data from GTEx." (PMID 39247186, 2024). "In contrast, inhibition of ACAT1 activity promoted the proliferation of gastric cancer cells." (PMID 39247186, 2024). "Collectively, our data show that ACAT1 induces pronounced inhibitory effects on gastric cancer initiation and development, which may impact future strategies to treat this aggressive cancer." (PMID 39247186, 2024). "Besides, we analyzed the correlation of ACAT1 expression with prognosis of gastric cancer patients from the TCGA database." (PMID 39247186, 2024). "Further research is needed to evaluate the functional role of ACAT1 in gastric cancer." (PMID 39247186, 2024). "In addition, there was a significant decrease in ACAT1 expression in gastric cancer samples when compared to corresponding adjoining samples." (PMID 39247186, 2024). "In summary, we found that the expression of ACAT1 is downregulated in advanced gastric cancer." (PMID 39247186, 2024).
gastric cancer (continued). "In addition, the low expression of ACAT1 in gastric cancer was further validated by searching public databases and conducting bioinformatic analyses." (PMID 39247186, 2024). "In summary, ACAT1 inhibits the stemness of gastric cancer cells." (PMID 39247186, 2024). "Likewise, analysis of Human Protein Atlas (HPA) data revealed a decrease in ACAT1 protein expression in gastric cancer tissue when compared to normal tissue." (PMID 39247186, 2024). "However, gastric cancer patients with high expression of ACAT1 perform better than those with low expression of ACAT1 in the PFS curve." (PMID 39247186, 2024). "Furthermore, the decrease in ACAT1 expression in gastric cancer samples compared to normal samples were confirmed using the GEO datasets (GSE27342)." (PMID 39247186, 2024). "This supports our finding that downregulation of ACAT1 promotes EMT in gastric cancer." (PMID 39247186, 2024). "Moreover, our Transwell experiments revealed that ACAT1 inhibits the migratory and invasive abilities of gastric cancer cells, indicating that ACAT1 disrupts the EMT process." (PMID 39247186, 2024). "In this study, we investigated the correlation between ACAT1 expression and gastric cancer." (PMID 39247186, 2024). "Moreover, the ability of gastric cancer cells to form colonies on soft agar was also reduced by ACAT1 overexpression." (PMID 39247186, 2024). "Notably, there was a marked reduction in ACAT1 expression in late-stage gastric cancer compared to early stage cancer tissues, suggesting that ACAT1 may have an inhibitory effect on the progression of gastric cancer." (PMID 39247186, 2024). "Additionally, ACAT1 suppresses the growth of gastric cancer xenograft tumors in nude mice." (PMID 39247186, 2024). "Likewise, overexpression of ACAT1 inhibited epithelial mesenchymal transition (EMT) in gastric cancer cells evidenced by increased expression of the epithelial marker E-Cadherin, decreased expression of mesenchymal marker vimentin, and decreased expression levels of SNAI 1/3." (PMID 39247186, 2024). "K63 ubiquitination stabilizes PGK1 and recruits ACAT1, driving PGK1 acetylation and promoting tumor angiogenesis in gastric cancer." (PMID 41184227, 2025). "We investigated the relationship between ACAT1 and the levels of CD44 and OCT4 in three different gastric cancer cell lines." (PMID 39247186, 2024). "Hence, we hypothesized that ACAT1 may inhibit the establishment and progression of gastric cancer." (PMID 39247186, 2024). "To assess whether ACAT1 affects drug response of gastric cancer stem cells, we compared the drug response of MKN45-LV5 cells and MKN45-ACAT1 cells treated with 5-Fluorouracil (5-FU) and etoposide, two commonly used chemotherapy drugs in gastric cancer." (PMID 39247186, 2024). "ACAT1 inhibits the migration and invasion, EMT process, and survival of gastric cancer cells." (PMID 39247186, 2024). "In tissues from gastric cancer patients and in gastric cancer cell lines, we observed negative correlation between ACAT1 expression and TNM staging." (PMID 39247186, 2024). "However, there have been no reports on the involvement of ACAT1 in the progression of gastric cancer." (PMID 39247186, 2024). "A limitation of our study is the lack of a deeper mechanistic understanding the ACAT1’ s role in the stemness and EMT of gastric cancer cells." (PMID 39247186, 2024).
Hypercholesterolemia (2 papers, 2012 to 2022). An increased concentration of cholesterol in the blood. "Based on that, we suggest hypercholesterolemia and pravastatin treatment modulates MAM stability, which affects Acat1 activity and foam cell formation." (PMID 35372506, 2022). "There is also a sex (male)-specific association of ACAT-1 rs1044925 SNP and serum HDL-C and ApoAI levels in subjects with hypercholesterolemia but not in subjects with hypertriglyceridemia." (PMID 22243772, 2012).
hyperinsulinism (2 papers, 2018 to 2022). Abnormally high levels of insulin in the blood. "Therefore, lipotoxicity and hyperinsulinism induced by LDL were regulated by the natural compound auraptene, a geranyloxyn coumarin modulator of cholesterol-esterification by ACAT1 enzyme inhibition." (PMID 36005626, 2022). "Auraptene treatment ameliorated hyperinsulinism coupled with high ABCA1 levels, which maintained cholesterol homeostasis; therefore, the activity of cholesterol transport and the inhibition of cholesterol esterification through ACAT1 could play a significant protective role." (PMID 36005626, 2022).
Insulin resistance (2 papers, 2010 to 2021). Increased resistance towards insulin, that is, diminished effectiveness of insulin in reducing blood glucose levels. "We have also previously shown that ACAT1 expression was reduced in older individuals, which was associated with insulin resistance and a blunted stimulation of IMCL turnover in response to exercise." (PMID 33464721, 2021).
ischemic stroke (2 papers, 2014 to 2017). A stroke disorder caused by obstruction of blood flow to the brain, due to thrombotic (local blood clot formation) or embolic (due to a blood clot or other material traveling from another site) event. "Furthermore, they performed another study in 1730 unrelated subjects to identify the association between rs1044925 polymorphism in ACAT-1 gene and the risk of CAD and ischemic stroke." (PMID 29179498, 2017).
kidney tumor (2 papers, 2022 to 2023). "The other 3 genes in the prognosis model associated with lipid metabolism regulation displayed the diagnostic potential to discriminate between normal and kidney tumor tissues: ACAT1, ANGPTL4 and ACAA2." (PMID 36829161, 2023). "Using IHC data from the Protein atlas database, we observed strong or moderate staining for ACAA2, ACAT1, ASRGL1, and AKR1B10, weak staining for ANGPTL4 and ABCC2 in normal kidney tissues and opposite staining results in kidney tumor samples." (PMID 36829161, 2023).
liver cancer (2 papers, 2024). An epithelial or non-epithelial malignant neoplasm that arises from the liver. "In liver cancer, ACAT1 acetylates GNPAT, stabilizing FASN and promoting lipid metabolism, thereby contributing to hepatocarcinogenesis." (PMID 38817856, 2024). "In liver cancer, ACAT1 promotes lipid metabolism and tumor occurrence by stabilizing FASN through the acetylation of GNPAT." (PMID 39247186, 2024).
liver fibrosis (2 papers, 2016 to 2023). "Moreover, a deficiency of the cholesterol metabolism-related gene Acyl-coenzyme A: cholesterol acyltransferase (ACAT1) or Niemann-Pick type C2 (NPC2) increases the levels of FC in HSCs, thereby exacerbating the progression of liver fibrosis." (PMID 37298640, 2023).
lymph node metastasis (2 papers, 2021 to 2024). "In addition, lymph node metastasis had an increased level of ACAT1 expression (P = 0.0429), while HMGCL was higher in liver metastasis compared with primary tumors (P = 0.0274)." (PMID 34584218, 2021).
neuroblastoma (2 papers, 2023 to 2025). Neuroblastoma (NB) is the most common solid, extracranial childhood tumor. "For example, it has been recently described that silencing ACAT1 promotes the differentiation of the neuroblastoma cell line SH-SY5Y." (PMID 39858520, 2025). "Since thiamine metabolism is involved in ACAT1-mediated neuroblastoma cell differentiation and CHA regulates PDH activity, we focused on the relationship between TPK1 and neuroblastoma cells differentiation." (PMID 37375824, 2023). "Treatment with CHA or abolishment of ACAT1 restored the oxidative phosphorylation (OXPHOS) of neuroblastoma cells." (PMID 37375824, 2023). "We conjectured that mitochondrial ACAT1 is involved in the differentiation of neuroblastoma cells induced by CHA." (PMID 37375824, 2023). "CHA promotes neuroblastoma differentiation by inhibiting mitochondrial ACAT1." (PMID 37375824, 2023). "CHA induces the differentiation of neuroblastoma cells in vitro and in vivo by inhibiting ACAT1." (PMID 37375824, 2023). "The PCAT database showed that neuroblastoma patients with high TPK1 expression had corresponding low ACAT1 expression, suggesting a negative correlation between TPK1 and ACAT1." (PMID 37375824, 2023). "However, the relationship between ACAT1 and neuroblastoma differentiation has not yet been reported." (PMID 37375824, 2023). "In our study, PDH activity was significantly enhanced in both CHA-induced differentiated cells and ACAT1 knockdown cell lines, and OCR results showed that OXPHOS function was restored, suggesting that mitochondrial OXPHOS recovery may be an important factor driving neuroblastoma differentiation." (PMID 37375824, 2023).
renal cell carcinoma (2 papers, 2021 to 2024). "Our previous and present findings show that overexpressing the ketogenesis genes HMGCL and ACAT1, resulted in increased intracellular β-HB in both renal cell carcinoma and NPC, thereby inhibiting the growth capacity of tumor cells." (PMID 34485115, 2021).
triple-negative breast carcinoma (2 papers, 2023). An invasive breast carcinoma which is negative for expression of estrogen receptor (ER), progesterone receptor (PR), and human epidermal growth factor receptor 2 (HER2). "Remarkably, this extract also inhibited both tumor growth and ACAT-1 expression in triple-negative breast cancer xenograft mouse models." (PMID 37240264, 2023).
adenoma (1 paper, 2022). A neoplasm arising from the epithelium. "ACAT1 is also expressed in APAs and cortisol-producing adenomas, suggesting that ACAT1 participates in steroid production in tumor tissues." (PMID 36361592, 2022).
asthenozoospermia (1 paper, 2024). "The observed protein expression changes in ChAcDel/Del mice, particularly the increase in TOM20 and the decreases in IDH3A and ACAT1, offer insights into the molecular mechanisms underlying the mitochondrial dysmorphology and asthenozoospermia in these mice." (PMID 38275411, 2024).
B-cell lymphoma (1 paper, 2024). "Anti-CD19-CAR-T cells with silencing of ACAT1 exhibited an enhanced ability to kill B-cell lymphoma in vitro and in vivo." (PMID 38534399, 2024). "Taken together, all the data showed that silencing the ACAT1 gene could increase the efficiency of CD19-CAR in eradicating B-cell lymphoma." (PMID 38534399, 2024). "Moreover, the knockdown of ACAT1 led to better anti-tumor efficacy of anti-CD19 CAR-T cells in the B-cell lymphoma mice model." (PMID 38534399, 2024). "In summary, the current study revealed that silencing of ACAT1 enhanced the activation and cell proliferation of anti-CD19-CAR T cells, and the capacity of anti-B-cell lymphoma was also improved both in vitro and in vivo." (PMID 38534399, 2024).
Chlamydia pneumonia (1 paper, 2022). "ACAT1 expression was notably increased in THP-1-derived macrophages following the infection of Chlamydia pneumonia." (PMID 36387401, 2022).
colon adenocarcinoma (1 paper, 2021). "To interrogate the association of ACAT1 level with prognosis in CRC, we performed survival analysis and found that high ACAT1 expression is related to poor disease‐free survival in colon adenocarcinoma and rectum adenocarcinoma cohorts from The Cancer Genome Atlas (TCGA) cohort." (PMID 33463049, 2021).
colorectal tumor (1 paper, 2025). "Furthermore, by mouse tumor models and flow cytometric analysis, we confirmed that ACAT1 promoted cytotoxic NK cell infiltration into tumors and impacted colorectal tumor growth." (PMID 40289129, 2025). "Furthermore, orthotopic models also revealed that Acat1 impaired colorectal tumor growth." (PMID 40289129, 2025). "However, other regulators modulating ACAT1 pS60 may exist, and we are optimistic that PPM1A or other yet-unidentified regulators will hold promise for inhibiting colorectal tumor growth via specific induction of ACAT1 nuclear translocation." (PMID 40289129, 2025).
congenital adrenal hyperplasia (1 paper, 2018). Congenital adrenal hyperplasia (CAH) is an inherited endocrine disorder caused by a steroidogenic enzyme deficiency that is characterized by adrenal insufficiency and variable degrees of hyper or hypo androgyny manifestations, depending of the type and the severity of the disease. "Recent in vivo pharmacologic studies in healthy dogs have provided support for development of ATR-101 in ACC and endocrine diseases such as CS and congenital adrenal hyperplasia given that ATR-101 preferentially distributes to the adrenal glands and selectively inhibits adrenal ACAT1 activity." (PMID 29720169, 2018).
COVID-19 (1 paper, 2024). A disease caused by infection with severe acute respiratory syndrome coronavirus 2. "The expression levels of ACAT1 and CTSL show opposite trends in AD patients and COVID-19 patients." (PMID 38257800, 2024).
dyslipidemia (1 paper, 2025). "While dyslipidemia and cholesterol accumulation have been strongly implicated in promoting pathological NV in models of subretinal NV15, not much is known about role of cholesterol metabolism, activation of ACAT1/SOAT1, and CE formation in pathological RNV during ischemic retinopathy." (PMID 40603564, 2025).
gallstones (1 paper, 2025). Solid crystalline precipitates in the biliary tract, usually formed in the gallbladder, resulting in the condition of cholelithiasis. "Isoform-specific differences in ACAT activity may provide an additional mechanistic explanation, with ACAT2 particularly implicated in gallstone formation, whereas altered ACAT1-driven macrophage esterification may contribute more prominently to cholesterolosis." (PMID 41010704, 2025).
gynecological cancers (1 paper, 2020). "Additionally, the fact that inhibitors of ACAT-1 exhibited strong cancer-specific therapeutic potential in other cancers merits further investigation into gynecological cancers as well." (PMID 31978092, 2020).
hypercoagulability (1 paper, 2025). "This reduction in cholesterol content positively regulates cholesterol esters synthesis mediated by ACAT1, consequently reducing cholesterol esters accumulation in the liver and blood and alleviating the blood hypercoagulable state and ameliorating symptoms of early NONFH." (PMID 40988117, 2025). "In conclusion, JHP ameliorates early NONFH by regulating lipid metabolism, improving hypercoagulability, and restoring bone homeostasis through the NMNAT1/NMNAT3/NAMPT/STK11/HMGCR/ACAT1 axis." (PMID 40988117, 2025).
invasive ductal carcinoma (1 paper, 2020). "The feature plots and spatial feature plots were utilized to illustrate the distribution and expression of CIRBP, FAM110B, ACAA1, ACAT1, and DHCR7, showing that these key genes were highly expressed in the invasive ductal carcinoma tissue (cluster 2, 5, 8)." (PMID 32984314, 2020).
lung injury (1 paper, 2022). "The inhibition of ACAT1 weakened pulmonary inflammation and inhibited macrophage activation in bleomycin-induced acute lung injury." (PMID 36387401, 2022).
lymphoma (1 paper, 2024). A malignant (clonal) proliferation of B- lymphocytes or T- lymphocytes which involves the lymph nodes, bone marrow and/or extranodal sites. "Inhibition of cholesterol metabolism-related factors ACAT1 and SR-BI has led to the accumulation of free cholesterol, which suppressed lymphoma growth and increased the cytotoxic effects of chemotherapy drugs." (PMID 39144147, 2024).
minimal change disease (1 paper, 2025). "Notably, three proteins—ACAT1, MME, and FBP1—with the highest expression levels observed in minimal change disease (MCD) showed kidney tissue specificity." (PMID 40283082, 2025).
nutritional deficiency (1 paper, 2025). "While, characteristics of the malignant TME such as nutritional deficiency and glucose deprivation can downregulate ACAT1 pS60 to promote immune evasion." (PMID 40289129, 2025).